DUSP10 (dual specificity phosphatase 10)
Description:
Protein phosphatase involved in the inactivation of MAP kinases. Has a specificity for the MAPK11/MAPK12/MAPK13/MAPK14 subfamily. It preferably dephosphorylates p38.
Synonyms: MKP-5; MKP5
Tractability: Small molecule: a structure with a bound ligand is known. PROTAC: ubiquitination databases record sites on it; a small molecule that binds it is known.
Target class: Phosphatase; Serine/threonine/tyrosine protein phosphatase; Enzyme; Protein Phosphatase
Gene: Protein-coding gene on chromosome 1 (221,700,669 to 221,742,089, reverse strand). Ensembl gene ENSG00000143507.
Subcellular location: Cytoplasm; Nucleus
Subcellular location (Human Protein Atlas): Cytosol; Nucleoplasm
Pathways (Reactome):
Signal Transduction: Negative regulation of MAPK pathway; RAF-independent MAPK1/3 activation
Disease: Signaling by MAPK mutants
Gene Ontology:
Molecular function: JUN kinase binding; MAP kinase phosphatase activity; mitogen-activated protein kinase p38 binding; phosphatase activity; protein binding; protein serine/threonine phosphatase activity; protein tyrosine phosphatase activity; protein tyrosine/threonine phosphatase activity; MAP kinase tyrosine phosphatase activity; MAP kinase tyrosine/serine/threonine phosphatase activity
Biological process: dephosphorylation; negative regulation of JNK cascade; negative regulation of p38MAPK cascade; positive regulation of regulatory T cell differentiation; negative regulation of cell migration; negative regulation of epithelial cell migration; negative regulation of epithelial cell proliferation; negative regulation of epithelium regeneration; negative regulation of ERK1 and ERK2 cascade; negative regulation of oligodendrocyte differentiation; regulation of cell development; regulation of immune system process; regulation of multicellular organismal process
Cellular component: cytoplasm; cytosol; nucleoplasm; nucleus
Genetic constraint (gnomAD): Loss-of-function variants: 14 observed, 31.09 expected, observed/expected ratio (o/e) 0.45, 90% interval 0.3 to 0.7. The upper end of that interval is the gene's LOEUF score, 0.7, which puts it in group 2 of 6, group 1 being the genes least tolerant of losing a copy. Missense variants: 550 observed, 648.31 expected, observed/expected ratio (o/e) 0.85, 90% interval 0.79 to 0.91. Synonymous variants: 254 observed, 264.21 expected, observed/expected ratio (o/e) 0.96, 90% interval 0.87 to 1.07.
Homologues: Orthologues: chimpanzee DUSP10 (99% identical), macaque DUSP10 (99% identical), rabbit DUSP10 (98% identical), pig DUSP10 (97% identical), mouse Dusp10 (97% identical), dog DUSP10 (96% identical), rat Dusp10 (96% identical), guinea pig DUSP10 (93% identical), tropical clawed frog dusp10 (83% identical), zebrafish dusp10 (65% identical). Paralogues in human: DUSP16 (24% identical), DUSP8 (24% identical), DUSP7 (22% identical), DUSP4 (22% identical), DUSP6 (22% identical), DUSP1 (21% identical), DUSP9 (21% identical), DUSP2 (20% identical), SSH1 (19% identical), SSH2 (18% identical), SSH3 (18% identical), DUSP5 (17% identical), and 19 more.
Diseases named in the same sentence as DUSP10 in open-access papers:
DUSP10 is named in the same sentence as 66 diseases in open-access papers, as found by Europe PMC text mining. Sharing a sentence is not in itself a finding about the gene and the disease. The quoted sentences say what the papers report.
colorectal cancer (12 papers, 2018 to 2025). A primary or metastatic malignant neoplasm that affects the colon or rectum. "In favor of its effect on DUSP10, a separate GWAS for colorectal cancer associated rs6687758 with DUSP10." (PMID 29986742, 2018). "DUSP10 mRNA is frequently over-expressed in colon carcinoma and different polymorphisms (SNPs) have been identified near or within the sequence of DUSP10 gene, which are correlated with colorectal cancer (CRC) risk." (PMID 30939861, 2019). "For example, DUSP10 was highly expressed in colorectal cancer and promotes colorectal cancer cell proliferation by regulating the YAP signaling pathway." (PMID 36713584, 2022). "DUSP10 has been found to negatively regulate the inflammatory response and colorectal cancer cell growth." (PMID 36103219, 2022). "Overexpression of DUSP10 in human colorectal cancer (CRC) cells resulted in reduced tumor formation in immune deficient mice, and high DUSP10 expression was associated with better survival in CRC patients." (PMID 30967582, 2019). "Furthermore, DUSP10 is highly expressed in colorectal cancer (CRC) cell lines and promotes CRC cell proliferation via the regulator of yes-associated protein 1 (YAP1) activity." (PMID 36713584, 2022). "DUSP10 inactivates other MAPKs, such as extracellular signal-regulated kinase 1/2 (ERK1/2), p38, and c-Jun N-terminal protein kinase (JNK), which are involved in cellular proliferation and differentiation, enhancing the progression of colorectal cancer." (PMID 29464080, 2018). "While the exact contributions of ATF1, DUSP10 and CASC8 in TA remain to be further elucidated, our findings further support that genes involved in colorectal cancer may also be involved in tooth development and provide additional insights into deciphering the complex etiology of the condition." (PMID 29445242, 2018).
Obesity (6 papers, 2013 to 2025). Accumulation of substantial excess body fat. "Thus, DUSP10 downregulation by a specific inhibitor can increase brown adipogenesis and subsequently causes an anti-obesity effect via increased heat generation at the expense of ATP." (PMID 23977283, 2013). "Therefore, we speculated that an increase in microRNA-450a-5p expression in obesity models impairs glucose metabolism via DUSP10 downregulation." (PMID 39912972, 2025). "Adipose tissue-derived microRNA-450a-5p downregulated DUSP10 and impaired glucose tolerance and insulin sensitivity, and targeted inhibition of microRNA-450a-5p could improve obesity and T2DM, indicating the functional role of microRNA-450a-5p in obesity and T2DM." (PMID 39912972, 2025). "DUSP10 could be a valuable novel target for the treatment of obesity." (PMID 23977283, 2013). "Consequently, DUSP10 can be used as a novel target protein for the regulation of obesity." (PMID 23977283, 2013).
pancreatic cancer (6 papers, 2018 to 2025). "MiR-92a also activates the JNK signaling via targeting DUSP10 and is involved in regulating pancreatic cancer cell proliferation." (PMID 34082648, 2021). "In hepatocellular cancer and pancreatic cancer, miR-181 and miR92a, respectively, negatively regulate the DUSP10 expression, affecting the proliferation and migration of tumorigenic cells." (PMID 30939861, 2019). "Inhibition of the function of miR-92a-3p represses the proliferation of pancreatic cancer cells through the miR-92a-3p/DUSP10/JNK signalling axis." (PMID 29552296, 2018). "Additionally, miR-92a has also been found to promote pancreatic cancer cell proliferation via the DUSP10/JNK signaling pathway." (PMID 30804710, 2019). "Previous studies have reported that miR-92a is involved in the proliferation of human pancreatic cancer cells and differentiation of T cells into the Th1 phenotype via regulation of DUSP10/MKP5 expression." (PMID 40002789, 2025). "In human pancreatic cancer (PC), JNK activation through DUSP10 downregulation, which is directly targeted by miR-92a, promotes the proliferation of cancerous cells." (PMID 30939861, 2019). "miR-92a-3p is a known oncogene in other cancer and its role in PDAC has only been shown in pancreatic cancer cells where it targets JNK signaling pathway inhibitor, DUSP10 and promote JNK signaling and tumorigenesis." (PMID 31795960, 2019).
pulmonary fibrosis (6 papers, 2021 to 2025). Chronic progressive interstitial lung disorder characterized by the replacement of the lung tissue by connective tissue, leading to progressive dyspnea, respiratory failure, or right heart failure. "In contrast, mice with a systemic deletion of Dusp10, which is an equipotent phosphatase of JNK and p38 (also known as MKP-5), show clear resistance to BLM-induced lung fibrosis." (PMID 34204949, 2021).
viral infection (6 papers, 2019 to 2022). "tBHQ significantly changes the gene activities of genes that are involved in immune responses against virus infection, such as interferon signaling, prostaglandin synthesis (Ptgs1/2), and apoptosis (Dusp10)." (PMID 35629310, 2022). "This combined epigenetic and transcriptomic approach allowed for the proposal of candidate genes (e.g., DUSP10 encoding dual specificity phosphatase 10 and SLC44A1 encoding solute carrier family 44 member 1) for asthma and viral infection susceptibility." (PMID 33668787, 2021). "We should underline that a variety of stress stimuli such as sepsis, injury, chronic inflammation, and viral infection modulates DUSP10 expression." (PMID 30939861, 2019). "In contrast, a different virus infection (Influenza) induces DUSP10, reducing IRF3 nuclear accumulation that leads to downregulating type I IFN expression and T cell response in the lung epithelial cells." (PMID 30939861, 2019). "DUSP10 (MKP5) is expressed ubiquitously in the nucleus and cytoplasm, and is upregulated in response to viral infection: bone-marrow derived macrophages (BMDMs) infected with influenza virus or stimulated with poly(I:C) have enhanced DUSP10 mRNA and protein expression." (PMID 30764493, 2019).
asthma (5 papers, 2018 to 2023). "This suggests that decreases in DUSP10 lead to inflammation in airway diseases such as asthma, likely through regulating inflammasome activation." (PMID 30939861, 2019). "This suggests that DUSP10 has an important role in regulating inflammation of the airway and identifies it as a potential future therapeutic target for exacerbations of asthma and chronic obstructive pulmonary disease." (PMID 30333178, 2019). "COPD and asthma patients have been shown to have increased baseline levels of IL-1β; thus, DUSP10 may have an increased role in a disease setting." (PMID 30333178, 2019). "Thus, a potential role of DUSP10 in regulating the inflammasome has significant implications for asthma." (PMID 30333178, 2019). "Up-to-date, enhanced expression of DUSP10 has been reported in several malignancies such as colon, prostate, and breast cancer and diseases such as multiple sclerosis, atherosclerosis, diabetes, celiac disease, and asthma." (PMID 30939861, 2019). "Thus, although further studies focus on the role of Vdr in the expression of DUSP10 in Tpath2 cells and ILC2s are required, 1,25 (OH)2D3 could be involved in the control of Dusp10 expression, which may lead to the amelioration of the pathology of asthma." (PMID 30315197, 2018).
colon carcinoma (5 papers, 2013 to 2021). "Interestingly, the DUSP10 region has also been identified as a risk factor for colon cancer by a meta-analysis of three GWAS from the UK." (PMID 23936387, 2013). "It has been documented that DUSP10 had a higher expression in colon cancer tissue than normal tissues and was involved in regulating colorectal tumorigeneses, which was in correspondence with our results." (PMID 33996902, 2021). "A survival analysis of 167 colon cancer patients’ metastasis (GSE17538) showed significantly higher survival in low DUSP10 expression patients." (PMID 31717606, 2019). "A total of 1,580 eRNAs were successfully obtained from 521 colon cancer samples, of which LINC02257 was found to have the most significant impact on patients’ survival with its corresponding target gene DUSP10, making it our top key eRNA for colon cancer." (PMID 33996902, 2021). "The importance of this mechanism is strongly supported by nuclear DUSP10 and nuclear YAP1 presence in tumor tissue of colon cancer patients; and more importantly, poor prognosis is related to high nuclear DUSP10 expression." (PMID 31717606, 2019).
glioblastoma (5 papers, 2014 to 2025). The most malignant astrocytic tumor (WHO grade IV). "DUSP10 is phosphorylated by mTORC2 on Ser224 and Ser230 residues upon insulin stimulation, leading to stabilization of DUSP10 and subsequent inactivation of p38 in glioblastoma cells." (PMID 31151270, 2019). "Insulin treatment of U87 glioblastoma cells, which had been serum-starved for 18 h, resulted in the significant stabilization of DUSP10 as compared to control, unstimulated cells." (PMID 25568665, 2014). "We also noted that in glioblastoma cell lines harboring differential mTORC2 activity as a result of ectopic Rictor overexpression, DUSP10 mobility was altered in SDS-PAGE analysis." (PMID 25568665, 2014). "Furthermore, activation of the PI3K/Akt pathway by insulin has been shown to stabilize DUSP10/MKP5 in glioblastoma." (PMID 40002789, 2025). "Finally, we uncovered that DUSP10 was dramatically upregulated in glioblastoma (GBM) cells and that the knockdown of DUSP10 inhibited glioma cell proliferation and migration." (PMID 36713584, 2022). "In the glioblastoma lines U373MG, U87, and LN229 DUSP10 was degraded in a proteosome-dependent manner with a half-life of approximately 90 min, consistent with previous reports of the lability of other DUSPs." (PMID 25568665, 2014).
hepatocellular carcinoma (5 papers, 2019 to 2024). A malignant tumor that arises from hepatocytes. "For example, in human hepatocellular cancer, the expression of DUSP10 is elevated and promotes cancer cell metastasis through enhanced ERK activation." (PMID 36713584, 2022). "Downregulation of TP53INP1 has been reported to promote hepatocellular carcinoma cell metastasis through the p73/DUSP10 pathway and activation of ERK1/2." (PMID 32448269, 2020). "Additionally, loss of TP53INP1 has been found to promote metastasis in early-stage hepatocellular carcinoma cells through the DUSP10 phosphatase-mediated activation of the ERK pathway." (PMID 38436783, 2024). "Moreover, downregulated TP53INP1 promoted hepatocellular carcinoma cell metastasis through the p73/DUSP10 pathway and activation of ERK1/2." (PMID 32448269, 2020). "Previous studies have revealed that the downregulation of TP53INP1 could activate a p73-dependent DUSP10/ERK signaling pathway to promote the metastasis of hepatocellular carcinoma." (PMID 32477928, 2020). "In human hepatocellular cancer (HC), low expression of p73 (TP53INP1) diminishes its binding as transcription factor to DUSP10 promoter, downregulating the phosphatase expression, and promoting metastasis via increased ERK activation." (PMID 30939861, 2019).
breast cancer (4 papers, 2017 to 2022). A primary or metastatic malignant neoplasm involving the breast. "Twenty of the 27 common genes have published data presenting that these genes were associated with breast cancer, but seven genes (DUSP10, GABRA6, GABRR1, KIF21B, KLHL24, MAP2K2, and SLC10A1) might be passenger genes or have not yet been studied regarding their pathological roles in breast cancer." (PMID 28973975, 2017). "Next, RNA and protein expression of CCND3, DUSP10 and RAP1GAP was evaluated on breast cancer cell lines with known gene expression data to assess the correlation between gene and protein expression of these genes." (PMID 34440000, 2021).
melanoma (4 papers, 2019 to 2022). A malignant, usually aggressive tumor composed of atypical, neoplastic melanocytes. "We further validated the results from our screen by individually silencing the expression of DUSP4 and two other DUSP family members with roughly similar substrate selectivity (DUSP6 and DUSP10) in two different BRAFV600E melanoma cell lines." (PMID 35580987, 2022). "Our findings highlight the potential therapeutic benefit of combining chemotherapy with B7-H3 inhibition, and indicate that B7-H3 mediated chemoresistance in melanoma cells is driven through a mechanism involving DUSP10-mediated inactivation of p38 MAPK." (PMID 30967582, 2019). "Taken together, we have discovered a novel mechanism that contributes to B7-H3-mediated drug resistance through attenuating DUSP10 expression thereby activating p38 MAPK in melanoma cells." (PMID 30967582, 2019). "Our in vitro and in vivo results also suggest an anti-oncogenic role for DUSP10 in melanoma." (PMID 30967582, 2019). "A further analysis of MAPK regulatory genes showed that mRNAs for several DUSPs-DUSP1 DUSP5, DUSP8, DUSP10 and DUSP14-were upregulated in intrinsically MAPKi-resistant melanoma cell line." (PMID 35999349, 2022).